CXCR4 (C-X-C motif chemokine receptor 4)
Diseases named in the same sentence as CXCR4 in open-access papers (continued):
Sharing a sentence is not in itself a finding about the gene and the disease.
tumor (continued). "Moreover, inhibition of CXCR4/SDF1 axis using AMD3100 (Plerixafor), an agonist for CXCR4, has been shown to decrease AML tumor burden in AML leukaemic mice in combination with conventional AML chemotherapy." (PMID 25294819, 2014). "In contrast, a marked attenuation of tumor metastases was observed, suggesting that the CXCL12/SDF-1α and CXCR4 may regulate metastases in an angiogenesis-independent manner." (PMID 24971349, 2014). "Immunohistochemistry of tumor tissue sections obtained from PANC-1 xenografts reveals that the single treatments reduced the expression of the ALDH1, CD44, Sox2, CxCR4 and Ki-67, and induced cleavage of Caspase-3, whereas both treatments together had strongest effects." (PMID 25015789, 2014). "Thus, the correlation of CXCR4 and CXCL12 expression levels and tumor invasiveness was proposed to be exploited as potential early diagnostic biomarkers, one of the major challenges in diagnosis and treatment of invasive tumors." (PMID 25484899, 2014). "The present results clearly demonstrate the inhibitory effects of a CXCR4-specific antagonist on PC-3 tumor growth in nude mice, although AMD3100 treatment had no direct effect on the proliferation of PC-3 cells in vitro." (PMID 24137439, 2013). "Tumors derived from secondary and tertiary xenografts of THJ-11T cells consistently reproduced the primary tumors at the histological level, and Western blotting and immunohistochemical analysis confirmed the expression of tumor markers ALDH, CD44 and CXCR4 in the xenografts." (PMID 23724124, 2013). "Overexpressing CD164 in hOSE cells may have the ability to induce tumor cell growth, proliferation, migration and self-renewal mediated through the induction of SDF-1α and CXCR4, which activates the SDF-1α/CXCR4 signaling pathway." (PMID 24094005, 2013). "It is of note that CXCR4 and CXCR7 are present on both tumor cells and vascular cells." (PMID 23865743, 2013). "The membranous CXC chemokine receptor 4 (CXCR4) and its ligand, stromal-derived factor-1 (SDF-1), which is also known as CXCL12, are members of the chemokine family and their critical and active roles have been demonstrated in tumor growth and malignancy." (PMID 23381805, 2013). "A striking observation in our study was that treatment with paclitaxel, although reducing primary tumor volume, increased significantly the number of metastatic nodules, angiogenesis (and VEGF and SDF-1 levels in tumor cells) and expression of ALDH, SOX2, CXCR4 and SDF-1 in vivo." (PMID 24278179, 2013). "Recently, in fact, Zhu and colleagues have demonstrated that MSC release exosomes able to strongly trigger VEGF- and CXCR4-mediated pathways in tumor cells through the activation of Erk 1/2 and p38 MAPK kinases, thus resulting in an enhanced angiogenesis and tumor growth in vivo." (PMID 23466882, 2013). "The chemokine receptor CXCR4 and its chemokine CXCL12 are involved in normal tissue patterning but also in tumor cell growth and survival as well as in the recruitment of immune and inflammatory cells, as successfully demonstrated using agents that block either CXCL12 or CXCR4." (PMID 23449983, 2013). "Previous studies in other tumor types suggested a malignancy-enhancing activity of CXCR7 even in the absence of CXCR4." (PMID 24040160, 2013). "These marked differences in the biological effects of CXCR4 inhibition observed in animals and in cell culture may be explained by the fact that SDF-1 acts at multiple levels in the tumor microenvironment." (PMID 24137439, 2013). "It has been reported that epidermal growth factor, platelet-derived growth factor, stromal cell-derived factor-1/CXCR4, SCF/c-Kit and vascular endothelial growth factor (VEGF)/VEGF receptor (VEGFR) 1 and VEGFR2 may play a role in the tumor-tropic effects." (PMID 24040358, 2013). "Moreover, while some chemokine receptors, such as CXCR4 and CCR7, have been extensively studied, additional studies are needed to examine the role of other chemokines in tumor progression and metastasis." (PMID 24259307, 2013).
tumor (continued). "CXCR4 and CXCL12 recruit monocytes and regulatory T cells (Tregs) into the tumor microenvironment." (PMID 24312199, 2013). "Interestingly, the expressions of MIF and CXCR4 in tumor cells and in TILs were significantly positively correlated (P < 0.05), and the combined MIF and CXCR4 expression in tumor cells was an independent adverse predictive factor for DFS and OS (P < 0.05)." (PMID 23497377, 2013). "We found that the CXCR4 inhibitor AMD 3100 reduces wound-promoted tumor growth without significantly affecting tumor growth in unwounded animals, strongly suggesting that wound-derived SDF-1α, one of the splice variants of SDF-1, increases tumor growth." (PMID 23593347, 2013). "To determine whether CXCL12 effects were mediated by CXCR4, we treated cultures with AMD3100 and measured tumor cell growth by bioluminescence imaging." (PMID 22427929, 2012). "In the primary tumor tissue of these patients (n = 14), a significantly positive correlation (p = 0.036) could be observed between high HER2 (57.14%) and high CXCR4 (42.86%) expression." (PMID 23082154, 2012). "However, the impact of circulating HCs and EPCs on vasculogenesis and sprouting angiogenesis in tumor angio-development is still controversially discussed in the literature, and the role of the SDF-1/CXCR4 pathway is not yet fully understood." (PMID 21977032, 2012). "Moreover, the aim was to further investigate the role of CXCR4 and HER2 in primary tumor growth and in the homing of metastases." (PMID 23082154, 2012). "Blocking SDF-1/CXCR4 interaction with a CXCR4 antagonist, AMD3100 (1,10-[1,4-phenylenebis(methylene)]bis-1,4,8,11 -tetraazacyclotetradecane octahydrochloride), inhibited metastatic tumor growth in a mouse hepatic metastasis model." (PMID 22871210, 2012). "Combined CXCR4/CXCR7 expression has been detected in primary human tumors and tumor cell lines." (PMID 22916293, 2012). "In experimental models, treatment with CTCE-9908 showed to reduce tumor burden, but did not reduce the frequency of metastasis suggesting that other mechanisms independent from the expression of CXCR4 are involved in metastasis development." (PMID 22433180, 2012). "Actually, CXCR4 and VEGF are the collaborators in tumor metastasis." (PMID 23300882, 2012). "In particular, we have previously shown that CXCR4 mostly promoted NB primary tumor and secondary growth, without influencing organ-specific dissemination of malignant NB cells." (PMID 22916293, 2012). "To assess whether CXCR4 plays a direct role in tumor activities, we silenced CXCR4 in SW1116 cells by CXCR4 shRNA and examined the function of CXCR4 knockdown on tumor proliferation, adhesion and invasion." (PMID 23071744, 2012). "Indeed, the abundance of CXCR4 was diminished on the surface of SW1116 cells following endostar and oxaliplatin treatments, providing an explanation for the reduced tumor growth and metastasis." (PMID 23071744, 2012). "In human ACP samples, CXCR4 expression was not very abundant and broadly expressed throughout the tumour with weak up-regulation in some clusters." (PMID 22349813, 2012). "Several studies demonstrated that: a) the expression of chemokine receptors in neoplastic cells is not random; b) CXCR4 is the most widely expressed chemokine receptor in most tumours; c) the effects of SDF-1 on CXCR4-expressing cancer cells are pleiotropic." (PMID 22417013, 2012). "Four normal tissue samples, derived from non-neoplastic mammary glands resected during tumor surgery, were included in the study as CXCR4 expression reference." (PMID 22417013, 2012). "However, the relative contribution of the CXCR4/CXCL12 axis in organ-specific dissemination or/and tumor growth has been strongly debated." (PMID 22916293, 2012). "Noteworthy, stromal CXCL12 expression was detectable in nearly all cases (in 95% (41/43) of therapy-naïve cases and in all metastatic lesions), regardless of CXCR4/ CXCL12 expression by tumor cells." (PMID 23249693, 2012).
tumor (continued). "Bioluminescence imaging 48 hrs post-intracranial injection was similar between the two groups [mean photon flux for sc-U87-Luc: 6.78×106; and for shCXCR4-U87-Luc: 7.17×106] suggesting that CXCR4 was not required for tumor cell engraftment." (PMID 22427929, 2012). "Thus, we evaluated the levels of secreted SDF-1 in tumors under different ZHENG conditions, and the expression of CXCR4, the SDF-1 cognate receptor, in tumor cells." (PMID 22690248, 2012). "Although several hypotheses on the role of CXCR7 and its possible interaction with CXCR4 have been proposed in different tumor systems, the functional implication of the global CXCL12/CXCR7/CXCR4 axis in NB remains unknown." (PMID 22916293, 2012). "Interestingly, different chemokine receptors direct tumor cells to specific organs in a mouse model, for example, CCR7, CCR10, and CXCR4 to lymph node, skin, and lung metastasis, respectively." (PMID 23342280, 2012). "CXCR-4 is an alpha-chemokine receptor specific for CXCL12 (also called stromal-derived-factor-1 or SDF-1), a molecule endowed with potent chemotactic activity for lymphocytes and tumor cells." (PMID 22074556, 2011). "Our data show that in the setting of hypoxia and CXCR4 up-regulation in Treg, CXCL12 expression may have the negative consequence of enhancing Treg recruitment and suppressing the anti-tumour immune response." (PMID 21521526, 2011). "The interaction of SDF-1 with CXCR4 has been shown to play a role in tumour metastasis by CXCR4-expressing tumour cells migrating to normal tissues expressing SDF-1." (PMID 21587260, 2011). "Since CXCL12 is also known to act as a chemoattractant for MCs, we reasoned that MC migration into the tumor tissues might be the result of an interaction between CXCL12 and CXCR4." (PMID 21949886, 2011). "This may be the case also with chemokine receptor CXCR4, which was another gene that was strongly expressed in ESFT primary tumor samples." (PMID 22084725, 2011). "We show that CXCR4 overexpression increases chemotactic and invasive behavior, both in vitro and in vivo, in response to a CXCL12 gradient, as well as enhances the motile behavior of tumor cells within the primary tumor and their ability to intravasate." (PMID 22152016, 2011). "Here we report that CXCR4 overexpression increases the chemotactic and invasive behavior of MTLn3 cells, in vitro and in vivo, to CXCL12, as well as their motile behavior within the primary tumor." (PMID 22152016, 2011). "Our results indicate for the first time that plumbagin downregulated the expression of CXCR4 in different types of tumor cells, irrespective of the cell type and HER2 status." (PMID 21880153, 2011). "Survival is only 10% in tumor samples that express CXCR4 mRNA, compared to 90% survival in tumor samples that do not express CXCR4 mRNA." (PMID 21234386, 2011). "We found that blocking CXCR4 by expressing CXCL12(P2G) did not alter primary tumor growth, demonstrating the metastasis-specific effect of this antagonist." (PMID 20849618, 2010). "Even those tumours (n = 6), showing a faint CXCR4 positivity in the primary tumour, lacked CXCR4 expression in the corresponding lymph node metastases." (PMID 20386750, 2010). "The interaction of CXCR4 and CXCL12 may promote tumor progression and metastasis via the induction of VEGF-mediated angiogenesis." (PMID 20953377, 2010). "Interactions between CXCR4 and its ligand CXCL12 (stromal cell-derived factor 1, SDF-1) play an important role in the directional regulation of hematopoiesis, migration of hematopoietic cells, angiogenesis, and migration of metastatic tumor cells." (PMID 20953377, 2010). "Three lymph node metastases revealed vascular CXCR4 expression while tumour cells completely lacked CXCR4 in all cases." (PMID 20386750, 2010). "Moreover, we provided mechanistic evidence that MKP-1 suppresses both tumour proliferation and metastasis via promoting mesenchymal-to-epithelial transition followed by the dampening of MMP-2 and CXCR4 activities." (PMID 20226009, 2010).
tumor (continued). "Interestingly, the expression of CXCR4 in microvessels correlated highly significantly with the local tumour growth (T-category; p = 0.0001) as well as with the UICC-tumour stage (p = 0.0059)." (PMID 20386750, 2010). "We hypothesized that even though the substantial amount of AT-MSC could not be detected in tumors, they actually might have homed very early into the site of tumor growth and SDF-1α/CXCR4 axis could have been responsible for the homing." (PMID 20509882, 2010). "In the present study, we postulated that E6 and E7 expression could also strengthen tumor cell capability to home into distant metastatic sites in conjunction with microenvironmental stimuli, including the SDF-1α/CXCR4 axis." (PMID 19325708, 2009). "In multivariate analysis, CXCR4 expression, poorly differentiated tumour and LN metastasis were negative independent prognostic factors for OS whereas LN metastasis and poorly differentiated tumour were negative prognostic indicators for DFS." (PMID 19352387, 2009). "In multivariate analysis, high CXCR4 expression, LN metastases and poorly differentiated tumour are independent negative prognosis factors." (PMID 19352387, 2009). "CXCR4, the receptor for the chemokine stromal-derived factor 1 (SDF-1), has been shown to mediate many of the processes essential for cancer progression such as tumor cell proliferation, metastasis, and angiogenesis." (PMID 20028517, 2009). "None of the other parameters − cancer stage, tumour differentiation, vascular and perinervous embols − had a significant relationship to CXCR4 expression." (PMID 19352387, 2009). "The remaining foci comprised CXCR4-positive tumor cells, suggesting that blockade was not total (‘Ab anti-CXCR4’)." (PMID 19325708, 2009). "CXCR4 expression was found on NSCLC tumors and at sites of tumor metastasis." (PMID 19563666, 2009). "TGF-β has an additional role in cancer to promote bone metastasis by regulating many of the tumor-secreted factors that stimulate tumor growth and bone destruction, such as PTHrP, IL-11, connective tissue growth factor (CTGF), the CXC chemokine receptor 4 (CXCR4), and others." (PMID 19727403, 2009). "They alsoreported a positive correlation between strong CXCR4 expression and poortumor-specific survival independent of tumor stage and differentiation grade.The latter is in contrast to the results obtained in our study." (PMID 19266088, 2008). "Different CXCR4 expression was observed between the non-metastasized and metastasized cells, and observed among the tumour node metastasis (TNM) stages (P=0.012, 0.005, respectively)." (PMID 19002187, 2008). "Tumours in both the heparin and dp12-treated mice showed a small, but non-significant (P>0.05), decrease in the expression of CXCR4 mRNA in comparison with PBS-treated animals." (PMID 17726466, 2007). "The natural ligand of CXCR4, the stromal cell-derived factor (SDF-1 or CXCL12), is highly expressed in lung, liver, and lymph nodes, the preferred organs for metastasis of several tumours." (PMID 17245339, 2007). "In this study, we investigated the contribution of CXCR4 to NB progression in vitro and in vivo and demonstrate that CXCR4 overexpression promotes NB primary and secondary tumour growth but not NB invasion." (PMID 17925864, 2007). "For Kaplan–Meier plots with patients with malignant tumours, the parameters were dichotomised in two groups, one with low HER2/neu or cytoplasmic CXCR4 expression or SDF-1 abundance and one with medium or high (2/3) expression/abundance of the corresponding protein." (PMID 17245339, 2007). "In addition, expression of CXCR4 was evaluated in 39 patients with HCC semiquantitatively and correlated with both, tumour and patients characteristics." (PMID 16819541, 2006). "SDF-1 exerts effects through its cognate receptor CXC chemokine receptor (CXCR4), which is the only physiological receptor for SDF-1 and is known to play roles in chemotaxis, haematopoiesis, vasculogenesis and tumour spread and metastasis." (PMID 15987445, 2005).